NFE2L1 (NFE2 like bZIP transcription factor 1)
Diseases named in the same sentence as NFE2L1 in open-access papers (continued):
Sharing a sentence is not in itself a finding about the gene and the disease.
tumor (17 papers, 2009 to 2025). "On one hand, this may result from NFE2L1 deficiency leading to ROS accumulation, which could activate dendritic cells (DCs) or enhance tumor antigen release, thereby promoting the recruitment and activation of CD4+ T cells and CD8+ T cells (marked by CD3e)." (PMID 40677211, 2025). "Furthermore, our in vivo experiments using NFE2L1−/+ mice revealed that the loss of NFE2L1 significantly reduced tumor growth and cell proliferation, supporting the notion that NFE2L1 promotes gliomagenesis." (PMID 40677211, 2025). "In vivo tumor growth is significantly inhibited in NFE2L1−/+‐deficient heterogeneous mice." (PMID 40677211, 2025). "Altogether, such debating results presage a good start for this topic to explore the potential roles for Nrf1/Nfe2l1 in the immune homeostasis along with anti-tumor immune and anti-inflammatory responses." (PMID 40703332, 2025). "Our initial analysis revealed that the mRNA expression of NFE2L1 was significantly greater in tumor samples from patients than in normal brain tissue." (PMID 40677211, 2025). "The shift in macrophage polarization from M2 to M1 has the potential to bolster antitumor immunity, further underscoring the pivotal role of NFE2L1 within the tumor immune microenvironment." (PMID 40677211, 2025). "As the present study solely evaluated the role of NFE2L1 as a regulator of GJB expression in tumor cells, further in vivo work will be required to understand the functional role of this signaling pathway more fully in the context of a complex TME." (PMID 38562019, 2024). "When we monitored NFE2L1 and NDUFA9 protein levels using six paired HCC and adjacent tissue samples, four cases showed clearly increased NFE2L1 expression in tumor compared to the surrounding tissue." (PMID 32942643, 2020). "Furthermore, the measurements of tumor diameter and surface area were substantially lower in the NFE2L1 heterozygous group than those observed in the control group." (PMID 40677211, 2025). "The research suggests that taurine may affect the tumor immune response via the Nfe2l1-ROS-PD-1 signaling pathway." (PMID 39867697, 2024). "Currently, NFE2L1 regulates cell differentiation in non-tumor cells." (PMID 39061827, 2024). "Moreover, the overexpression of TF NFE2L1 has been suggested to protect tumor cells by decreasing the toxicity of treatment." (PMID 33802957, 2021). "As a result, overexpression of NFE2L1 could protect tumour cells by decreasing the toxicity of treatment." (PMID 19755993, 2009). "Herein, we determined whether two antioxidant transcription factors Nrf1 (also called Nfe2l1, as a tumor repressor) and Nrf2 (as a tumor promoter) are required for glycolysis and other glucose metabolic pathways and also involved in the redox metabolic reprogramming induced by glucose deprivation." (PMID 32774674, 2020). "This mirrors past studies showing NFE2L1/MAFG promotes PD‐L1 via super enhancers and LPS, facilitating tumor immune escape." (PMID 40677211, 2025). "Research on the relevant molecular mechanism by which NAT10 regulates ferroptosis revealed that NAT10 affected ferroptosis, which is closely related to tumor cells, by influencing the key regulatory molecules GPX4 and NFE2L1 of ferroptosis." (PMID 41189569, 2025). "We investigated the expression of NFE2L1 and GPX4 in both normal and tumor tissues." (PMID 41189569, 2025). "The results demonstrated that the protein and mRNA levels of NFE2L1 and GPX4 were significantly increased in tumor tissues, whereas the ferroptosis marker proteins PTGS2, and CHAC1 were expressed at low levels in tumor tissues, however, SLC7A11 exhibited significant overexpression in tumor tissues." (PMID 41189569, 2025). "Next, we compared the NFE2L1 expression levels among tissue types with clinical aggravation in TCGA-LIHC and observed a tendency of increasing NFE2L1 from normal liver tissue to primary tumor and recurrent tumor." (PMID 32942643, 2020).
tumor (continued). "However, the role of NFE2L1 in the microenvironment of tumor tissues is not undetermined." (PMID 39061827, 2024).
neurodegenerative disease (5 papers, 2015 to 2025). A disorder of the central nervous system characterized by gradual and progressive loss of neural tissue and neurologic function. "Dysregulation of these processes due to NFE2L1 dysfunction has been implicated in several neurodegenerative diseases such as AD, PD, and HD." (PMID 40375958, 2025). "Dysfunction of NFE2L1 is implicated in several neurodegenerative diseases due to its inability to properly regulate oxidative stress responses and iron metabolism." (PMID 40375958, 2025). "This section will present evidence supporting a correlation, and possibly a causal link, between NFE2L1 dysfunction and neurodegenerative diseases, as observed in knockout mouse models and postmortem brain studies." (PMID 40375958, 2025). "The findings highlight Nfe2l1 as an emerging therapeutic target to treat neurodegenerative diseases linked to protein misfolding." (PMID 37450596, 2023). "The findings pave the way to consider the relatively poorly investigated Nfe2l1 pathway as a therapeutic target for treating neurodegenerative diseases linked to protein misfolding and promote drug development to enhance its activity." (PMID 37450596, 2023). "Therefore, here, we examined direct Nfe2l1 overexpression as an alternative approach to increase the pool of proteasomes in neurodegenerative diseases linked to impaired proteostasis in the retina." (PMID 37450596, 2023). "Additionally, we will explore how NFE2L1 influences ferroptosis, a form of programmed cell death implicated in neurodegenerative diseases, and the potential therapeutic benefits of targeting this transcription factor to restore proteostasis and protect neuronal function." (PMID 40375958, 2025). "NFE2L1 has emerged as a promising therapeutic target for neurodegenerative diseases due to its crucial role in regulating oxidative stress, protein turnover, and cellular resilience." (PMID 40375958, 2025). "NFE2L1 regulates neuroinflammation, iron homeostasis, and oxidative stress, key factors in neurodegenerative diseases." (PMID 40375958, 2025). "By enhancing proteasomal activity, NFE2L1 helps maintain protein homeostasis, preventing the accumulation of toxic protein aggregates that contribute to cellular dysfunction and neurodegenerative diseases." (PMID 40375958, 2025). "This review explores NFE2L1 as a key regulator of proteostasis in neurodegenerative diseases, highlighting its role in controlling autophagy, ferroptosis, and the proteasome." (PMID 40375958, 2025). "These in vivo models across different species and genetic alterations provide a clearer picture of the functional impact of NFE2L1 dysfunction in neurodegenerative diseases." (PMID 40375958, 2025). "The significance of NFE2L1-mediated proteostasis becomes particularly evident in the context of neurodegenerative diseases such as AD and PD, where impaired proteostasis is a hallmark of pathogenesis." (PMID 40375958, 2025). "By highlighting gaps in the current understanding and presenting future research directions, this review aims to elucidate NFE2L1’s role in advancing treatment strategies for neurodegenerative diseases." (PMID 40375958, 2025). "NFE2L1’s impact on ferroptosis regulation in neurodegenerative diseases." (PMID 40375958, 2025). "Given that neurodegenerative diseases are characterized by the accumulation of misfolded, heavily ubiquitinated proteins, it is hypothesized that dysfunction of NFE2L1 may contribute to the pathogenesis and progression of these diseases." (PMID 40375958, 2025). "In this review, we summarize the role of UPS impairment in aging and neurodegenerative disease etiology and consider the potential benefit of enhancing NFE2L1 function as a strategy to upregulate proteasome function and alleviate pathology in neurodegenerative diseases." (PMID 37759569, 2023).
neurodegenerative disease (continued). "We also explore the idea that increasing the activity of NFE2L1, a protein that increases expression of UPS components, could be a strategy to enhance proteasome function and reduce the impact of neurodegenerative diseases." (PMID 37759569, 2023).
metabolic disease (2 papers, 2020 to 2022). A congenital disorder (due to inherited enzyme abnormality) or acquired (due to failure of a metabolically important organ) disorder resulting from an abnormal metabolic process. "The novel NFE2L1/AMPK signaling pathway discovered in this study not only revealed the underlying mechanism of NFE2L1-related metabolic diseases but also highlight the crosstalk between redox homeostasis and metabolism homeostasis." (PMID 35614059, 2022). "The novel NFE2L1/AMPK signaling pathway delineate the mechanism underlying of NFE2L1-related metabolic diseases and highlight the crosstalk between redox homeostasis and metabolism homeostasis." (PMID 35614059, 2022). "Studies have revealed that NFE2L1 plays an important role in metabolic pathways and influences the development of metabolic diseases." (PMID 35614059, 2022).
Kidney Disease (1 paper, 2023). "We found that the expression of NFE2L1 was drastically reduced in podocytes in biopsies from kidney disease patients." (PMID 37681897, 2023). "In this study, we show that NFE2L1 expression is reduced in kidney disease, and in ex vivo and in vitro models of podocyte injury." (PMID 37681897, 2023). "In this study, we characterized the expression of multiple NFE2L1 protein isoforms in podocytes and demonstrated that NFE2L1 nuclear expression is reduced in podocytes from kidney disease patient biopsies and in injured podocyte cell lines." (PMID 37681897, 2023). "In addition, the KPMP Consortium study of the cell states in human kidney showed that mean expression of NFE2L1 RNA was reduced in kidney disease compared to the healthy reference." (PMID 37681897, 2023). "We found that both NFE2L1 and NQO1 expressions were significantly diminished across all observed renal diseases." (PMID 37681897, 2023). "In order to assess any altered expression of NFE2L1 and NF2EL2 proteins in kidney disease, renal biopsy samples were assessed using mIF and whole-slide image analysis." (PMID 37681897, 2023).
neurological diseases (1 paper, 2025). "It is known that the complete loss of NFE2L1 is embryonically lethal, suggesting that heterozygous mutations or SNPs in one allele, or reduced expression or activity of NFE2L1, may drive specific neurological diseases." (PMID 40375958, 2025).
NFE2L1 also shares sentences with these, for which no sentence is quoted: infection (2 papers); neuroblastoma (2); triple-negative breast carcinoma (2); viral infection (2); Adrenal insufficiency (1); allergic disease (1); Anxiety (1); cardiovascular disease (1); diffuse large B-cell lymphoma (1); esophageal carcinoma (1); glioblastoma (1); glomerulopathies (1); hematological malignancies (1); Hepatic steatosis (1); infectious disease (1); ischaemic stroke (1); Kennedy disease (1); kidney cancer (1); liver fibrosis (1); lymphoid neoplasm (1); mantle cell lymphoma (1); metastasis (1); multiple sclerosis (1); Neurodegeneration (1); osteoporosis (1); ovarian serous cystadenocarcinoma (1); pancreatic adenocarcinoma (1); pancreatic cancer (1); pulmonary fibrosis (1); skin tumors (1).
A further 4 diseases each share a sentence with NFE2L1 in 1 paper.